MUC4 (mucin 4, cell surface associated)
Diseases named in the same sentence as MUC4 in open-access papers (continued):
Sharing a sentence is not in itself a finding about the gene and the disease.
tumor (continued). "Our data indicated that MUC4 expression significantly correlated with the T grade and tumor stage." (PMID 26393880, 2015). "Furthermore, in the same study an in vivo experiment showed that miR-219-1-3p injection in xenografted PDAC mice reduced tumor growth through MUC4 oncomucin reduction." (PMID 26259238, 2015). "We also assessed MUC4 and netrin-1 expression in tumor tissues from nude mice." (PMID 26393880, 2015). "It is quite likely that we would have diagnosed this lesion as malignant mixed epithelial and stromal tumor of kidney (MEST) only a few years ago when typical genetic alterations or MUC4 staining characteristic of this tumor type were unknown yet." (PMID 26449317, 2015). "Thus, we found MUC4 locus to be the most altered in the tumour tissue compared to that in the control tissue." (PMID 25496518, 2014). "Our study provides evidence that MUC4/Y plays an initial role in tumor angiogenesis." (PMID 25367394, 2014). "MUC4 expression was related to tumor location (high for anal side, p = 0.012)." (PMID 24722639, 2014). "Thus, compared with neoplasms of other organs, MUC4 expression is of little significance in SBCs, similarly to MUC1." (PMID 24722639, 2014). "The tumor volume from MUC4 knockdown cells was significantly smaller (p = 0.0001) and the tumors excised at 8 weeks had markedly reduced weight, compared with tumors obtained from control cells (mean 0.171±0.05 g in MUC4 knockdown vs. 0.653±0.07 g in control cells)." (PMID 23408941, 2013). "Collectively, the existing evidence suggests that MUC4 has tumor-promoter functions." (PMID 24204934, 2013). "Both MUC4 and ErbB2 are overexpressed in several epithelial cancers (pancreas, breast, lung, oesophagus, colon, ovary) and both have been shown to play roles in tumour development." (PMID 22393391, 2012). "MUC4 can also promote tumor progression by repressing apoptosis by means of multiple mechanisms." (PMID 23101681, 2012). "To test this hypothesis, we performed intra-pancreatic injections of the broad tropism virus and of the MUC4 oncotropic virus in tumor-free mice." (PMID 23088623, 2012). "Interestingly, MUC4 expression was strongly repressed in ErbB2-KD tumours confirming the strong decrease in MUC4 level in ErbB2-KD cells observed by immunoblotting." (PMID 22393391, 2012). "In this report, we show that E2F1 and STAT1 are activators of MUC4 mucin tumor marker." (PMID 22537161, 2012). "Studies presented here show that it may also regulate the expression of genes like MUC4, which contribute to oncogenesis and tumor progression." (PMID 22537161, 2012). "We also show that they play roles in different properties of cancer cells with ErbB2 clearly affecting proliferation, cell cycle and tumour growth whereas MUC4 shows a wider spectrum of activities ranging from proliferation, cell cycle, tumour growth but also migration and invasion." (PMID 22393391, 2012). "Thus, the combination of anti-TR and anti-non TR MUC4 antibodies can provide better information about the extent of MUC4 overexpression in the tumor tissues." (PMID 21886786, 2011). "These antibodies could also aid in understanding MUC4 structure-function relationships, regulation of expression and possibly identify a probable interacting partner on the tumor cell surface, which could be the reason for the metastatic phenotype." (PMID 21886786, 2011). "Furthermore, Pea3 activates transcription of multiple neoplasia-associated genes, including MMP genes, COX-2, Twist, osteopontin, uPA, vimentin, MUC4, WT1, mammaglobin, cyclin D3 and HER2." (PMID 20107508, 2010). "A number of studies underscore the notion that MUC4 may be capable of contributing to the malignant properties of tumor cells." (PMID 19761616, 2009). "Moreover, the anti-apoptotic signaling properties of MUC4 can minimize the chances that primary tumor cells that have lost adhesion and are undergoing metastasis will undergo anoikis." (PMID 19761616, 2009).
tumor (continued). "Although work examining the impact of MUC4 on model tumor cell properties strongly supports the notion that the mucin can promote tumor progression, evidence that it might do so in human tumors has been harder to obtain." (PMID 19761616, 2009). "However, involvement of MUC4 in the progression of other tumor types has been more difficult to assess because normal tissues express abundant MUC4 and because cell lines often rarely express the protein." (PMID 19761616, 2009). "In these cases MUC4 overexpression relative to normal tissue, MUC4 mislocalization in cells that have lost their polarity, or re-expression of lost MUC4 in more advanced tumor stages, can all markedly impact disease progression but can be difficult to detect and characterize." (PMID 19761616, 2009). "Consistent with our immunoblotting results, MUC4 expression was significantly greater (P < 0.001) in normal tissue than primary tumor, whether looking at individual or paired samples." (PMID 19761616, 2009). "The increase in cell motility (P<0.05), which has a major role during the dynamic process of tumour invasion and metastasis, may be a direct result of MUC4-mediated changes in the actin organisation, or indirectly through an ErbB2-mediated pathway." (PMID 18781152, 2008). "Biliary MUC4 and serum MUC5AC are highly specific tumour-associated mucins that may be useful in the diagnosis and formulation of therapeutic strategies in BTC." (PMID 18475301, 2008). "Furthermore, in vivo tumorigenicity analysis revealed that animals transplanted with the MUC4 overexpressing cells (AGS-MUC4) had a greater incidence of tumours (83%) in comparison to empty vector control (17%)." (PMID 18781152, 2008). "MUC4 is known to inhibit tumour killing by lymphokine-activated killer cells." (PMID 15494719, 2004). "The SC tumour cells regained their ability to express MUC4 transcripts after in vitro culture." (PMID 14760381, 2004). "However, the in vitro culture of SC tumour cells resulted in the expression of MUC4 transcripts comparable with its expression level in the parental cell line CD18/HPAF." (PMID 14760381, 2004). "The MUC4-expressing OT tumours also showed transforming growth factor (TGF)β2 expression." (PMID 14760381, 2004). "Further, histological examination of the tumours revealed the OT tumours as moderately differentiated, whereas the SC tumours were poorly differentiated, suggesting that the expression of MUC4 could be influenced by the differentiation grade of tumours." (PMID 14760381, 2004). "The MUC4 protein contains several domains, each of which may promote tumor progression." (PMID 40649822, 2025). "Likewise, the critical role of MUC4 in tumor biology must be acknowledged and considered." (PMID 40655139, 2025). "MUC4 provides steric hindrance via its bulky, glycosylated extracellular region to mask immune cell surface antigens and shield tumor cells from immune recognition, thus enhancing survival and extravasation of metastasized tumor cells via interaction with macrophages and hematopoietic progenitors." (PMID 35522218, 2022). "Finally, MUC4 appears to play a role in gemcitabine chemoresistance, by inhibiting gemcitabine-induced apoptosis and increasing the level of transporters that remove gemcitabine from the tumor cells." (PMID 34522225, 2021). "Interestingly, TTN, PIK3CA, MUC4, KMT2C, and MUC16 were the top mutations in both cohorts, which were reported to regulate various tumor biological processes in CC, indicating that they are less participated in the process of immune infiltration but mainly involved in tumorigenesis and progression." (PMID 33553190, 2021). "Moreover, our findings indicate that miR-210-3p could be a good anti-tumor candidate by inhibiting both MUC4 expression and tumor initiation." (PMID 34944818, 2021).
tumor (continued). "MUC4 is an antigen that is normally not expressed in the pancreas but often appears in tumor cells and can induce the production of auto-antibodies and reactive T cells, especially against MUC4 forms carrying aberrant glycosylation patterns or mutations, or differing for alternative splicing." (PMID 33672007, 2021). "To investigate this possibility, we stained slices of fixed and embedded tumor tissue from whole resected tumors with antibodies against three proteins we selected from among the most differentially expressed transcripts: Tenascin C (Tnc), Mucin 4 (Muc4), and Cadherin 17 (Cdh17)." (PMID 34936674, 2021). "MUC4 is expressed at the surface of epithelial cells from gastrointestinal and respiratory tracts and has been studied in various cancers where it is generally overexpressed and described as an oncomucin and has been proposed as an attractive prognostic tumor biomarker." (PMID 30236127, 2018). "Moreover, we also found some genes that have not been identified as tumour-associated genes by Cancer Gene Census also encode potential neoantigens, such as MUC4, FAM194B, OPRD1 and FRG1." (PMID 28484631, 2017). "Therefore, MUC4/Y-AMOP domain-promoted tumour angiogenesis and metastasis may be partly due to the activation of NOTCH3." (PMID 27287498, 2016). "Finally, ErbB2-KD and MUC4-KD cells showed impaired tumour growth in vivo." (PMID 22393391, 2012). "All of these studies have shown that MUC4 could be a key player in tumorigenesis; however, all of these studies have analyzed MUC4 in tissue samples, which could be limited by sampling errors, due to the heterogeneous expression of tumor antigens." (PMID 21886786, 2011). "In addition, the anti-adhesive and anti-apoptotic properties of overexpressed MUC4 could provide tumor cells with a selective growth or survival advantage." (PMID 19761616, 2009). "However, it should be noted that MUC4 expression by a small subset of cells within the primary tumor mass may be sufficient to facilitate metastasis, and this population could easily be overlooked by immunohistochemical analysis." (PMID 19761616, 2009). "Indeed, given the potent anti-adhesive properties of MUC4, these tumor cell populations could express very high levels of MUC4 protein, which may again be suppressed to some degree upon metastatic seeding of a solid target tissue." (PMID 19761616, 2009). "Notably, even with the relatively modest core sizes, tumor emboli were often observed within lymphovascular spaces of lymph node tissue (arrowheads), where both the vasculature and the adherent epithelial emboli stained positively for MUC4." (PMID 19761616, 2009). "Thus, results suggest that MUC4, by increasing mitochondrial mass, most probably contributes to the redox status of the cells, which in turn provides the cancer cells with a survival advantage in pre-angiogenesis, leading to increased tumour progression." (PMID 17595659, 2007). "Immunohistochemically, the reported eight neoplasms showed variable expression of epithelial markers (AE1/AE3, EMA), six tumors showed MUC4 expression, and four cases were immunoreactive for CD99." (PMID 41341384, 2025). "The expression profiling of overexpressed MAMs explored the cancer‐specific overexpression of MUC3A, MUC4, MUC13, and MUC16 in tumor samples as compared to control." (PMID 41142718, 2025). "We observed close colocalization of MUC4 and CA125 in a subpopulation of tumor cells and a stronger KRT24 signal corresponding to these cells in two HVs." (PMID 40527915, 2025). "Apoptosis: Certain mucins, such as MUC4 and MUC21, have been shown to inhibit apoptosis and to promote tumor cell survival." (PMID 40655139, 2025). "The RT‐qPCR analysis revealed that all target genes (MUC3A, MUC4, MUC13, and MUC16) are significantly overexpressed in tumor samples as compared to control samples." (PMID 41142718, 2025). "The tumor cells showed positive expression for Vimentin, ERG, MUC4, TLE1, CD99, CD56, Ki67 (approximately 80%), and H3K27Me3." (PMID 40144208, 2025).
tumor (continued). "This mAb was highly specific for the MUC4 glycopeptide antigen in glycan microarrays, ELISA and SPR assays, selectively stained tissue derived from advanced-stage tumors, and bound MUC4+ tumor cells in flow cytometry assays." (PMID 40649822, 2025). "The presence of MUC4 can enhance cancer cell migration and promote EMT, thus facilitating metastasis through increased plasticity of tumor cells." (PMID 40655139, 2025). "In the tumor region, DEGs included ECM-related genes such as MMP7, LCN2, chemokine CXCL5, and tumor markers CLDN4 and MUC4." (PMID 40303346, 2025). "Selective expression of MSLN, MUC4, ANXA10, and GPC-1 in the neoplastic tissue compared to non-tumor ductal and acinar tissues (p < 0.001)." (PMID 39062863, 2024). "In our study, almost all neoplasms were positive for BCL2, CD99, CD56, FLI1, TLE1, MUC4, and PDGFR alpha." (PMID 39062853, 2024). "PanIN development coincided with the staining of classic tumor marker proteins, SERPINB5/Maspin and Muc4." (PMID 38672675, 2024). "Aberrantly expressed MUC4 can act as a ligand for ERBB2, potentiate the phosphorylation of ERBB2, and reduce the binding of anti-ERBB2 antibodies to tumor cell surfaces." (PMID 37367035, 2023). "A recent study showed the overexpression of MUC1, MUC19, MUC4, MUC5AC, and MUC5B in the mucinous metaplasia of tissues isolated from Pten conditional knockout mice and human PCa tumor tissues." (PMID 36980526, 2023). "These aberrantly expressed glycoproteins, including MUC1, MUC4, and MUC13 play important roles in tumor progression and treatment and are commonly referred to as tumor-related glycoproteins." (PMID 36118865, 2022). "The link between tumor and circulating hybrids is perhaps best demonstrated by the identification of the Y chromosome in CHCs (CK+/CD45+ and tumor-specific MUC4) in female recipients of sex-mismatched BMT who subsequently developed cancers." (PMID 36010865, 2022). "This tumor is usually positively stained with S-100, mammaglobin, CK7, MUC4, and GATA3, while in our patient the final diagnosis was based on the presence of ETV6 rearrangements which did not require immunohistochemical staining." (PMID 36186229, 2022). "Furthermore, MUC4 mutant samples presented a higher infiltration proportion of follicular helper T cells and activated memory CD4 T cells, which is in line with previous established evidence that anti-tumor immune response was associated with these immune cells and pathways." (PMID 33714943, 2021). "The FXR activated by bile acids also increased tumour progression by activating focal adhesion kinase (FAK)/c-Jun, Src, and mucin 4 (MUC4)." (PMID 35006466, 2021). "Through abnormal overexpression, MUC4 can interact with HER2 (a ligand-dependent receptor tyrosine kinase) physically and phosphorylated activate and stabilize HER2 to promote tumor invasion and metastasis." (PMID 34512870, 2021). "Immunohistochemistry showed that the tumor was positive for CK19, S-100, vimentin, mammagloblin, GCDFP15, and MUC4." (PMID 34941172, 2021). "With this interaction, MUC4 mediates HER2 and HER3 activation, thus enhancing signaling cascades such as MAPK, JNK, STAT-1, promoting tumor proliferation and metastasis 40-42." (PMID 34522225, 2021). "In our cases, immunostaining revealed that the tumor was positive for CK19, S-100, vimentin, mammaglobin, GCDFP15, GATA3, and MUC4." (PMID 34941172, 2021). "Knockdown of IL-17RB, MUC1 and/or MUC4 also suppresses expression of stemness-related markers, such as SOX2, Nanog, Oct-4, and CD44, and inhibited tumor sphere formation." (PMID 33082357, 2020). "The tumor cells stained diffusely positive for DOG1 with moderate staining density, and diffusely and strongly positive for MUC4." (PMID 32164724, 2020). "Overall, we suggest that TQ induces transcription of TTP and destabilizes mRNA of MUC4 oncogene by this TTP activity, resulting in the inhibition of tumor growth and metastasis." (PMID 31141941, 2019).
tumor (continued). "In the MUC4-positive JIMT1-tumors, the NAC-trastuzumab combination resulted in improved tumor-growth control compared to trastuzumab alone; with smaller tumor volume/weight, lower 18F-FDG uptake, lower %Ki67 and pAkt-expression." (PMID 28915583, 2017). "Furthermore, the disorganization resulting from MUC4 overexpression might pose a decreased effect on adhesion to other cells as well as the extracellular matrix, and therefore promoted the migration and metastasis of tumor cell." (PMID 27305093, 2016). "The results demonstrated that MUC4 and MUC20 were expressed at low levels in the tumor tissue samples obtained from chemosensitive patients (TRG1/2/3), whereas the expression of MUC13 did not significantly correlate with TRG." (PMID 26673820, 2016). "IHC was conducted to examine the expression of selected target markers MUC4, MUC13, and MUC20 in 186 ESCC resection samples and the relationships between their expression and tumor regression grade was analyzed." (PMID 26673820, 2016). "Our results show that canertinib pharmacologically reduces tumor burden by inhibiting EGFR family members and prevents metastatic events by down-regulating MUC4 mucin protein." (PMID 25686822, 2015). "Among miRNAs with tumor-suppressor activity in PDAC, miRNA-219-1-3p has recently been shown to inhibit the oncogenic mucin MUC4, largely involved in PDAC carcinogenesis." (PMID 26259238, 2015). "Moreover, MUC4 may possess a tumor-promotion function, in part by regulating HER2 gene expression." (PMID 24204934, 2013). "In pancreatobiliary differentiated tumours, MUC1 and/or MUC4 expression was an independent prognostic factor (hazard ratio 2.02, 95% confidence interval 1.02, 3.98) when adjusting for nodal involvement, vessel involvement and tumour size." (PMID 19236510, 2009). "The phenotypes CK7+ MUC4+ and CK7+ CDX2− optimally classified tumours as IHC pancreatobiliary, and the phenotypes CK7− and MUC4− CDX2+ optimally classified tumours as IHC intestinal." (PMID 19236510, 2009). "Consistent with the Northern blot and IHC, RT–PCR showed no expression of MUC4 in the normal human pancreas and the SC tumours, whereas a high level of MUC4 expression was found in the CD18/HPAF cell line and the OT tumours." (PMID 14760381, 2004). "Our results also indicated a direct correlation between the MUC4 expression and the levels of TGFβ2 transcripts in the CD18/HPAF tumours, as well as in CD18/HPAF cells in vitro." (PMID 14760381, 2004). "Tissue immunohistochemistry staining with the F5 mAb confirmed MUC4 expression in #133R tumor tissue and lack of detectable MUC4 in #295R tissue samples." (PMID 40649822, 2025). "IFN-γ can facilitate tumor metastasis by inducing the expression of ICAM1 and CD13, promoting epithelial-mesenchymal transition (EMT), and stimulating the production of CXCR4 and MUC4." (PMID 40143164, 2025). "Tumor cells were immunohistochemically positive for pan-cytokeratin, EMA, CD56, SOX10, and MUC4." (PMID 40151688, 2025). "Our study adds a third genetic tumor category with a variable SEF-like morphology with/or without MUC4 expression driven by FET::CREB fusions." (PMID 39031200, 2024). "MUC4, MUC16, and MUC17 were found in most tumor samples ( > 78%)." (PMID 38637560, 2024). "The expression of different mucins, like MUC1, MUC4, and MUC16, which are upregulated during cancer progression, may also inhibit apoptosis of tumor cells." (PMID 37207152, 2023). "One tumor expressed in addition AE1/AE3, MUC4, synaptophysin, chromogranin, and ALK." (PMID 37097347, 2023). "The variable expression patterns of MUC2 (i.e., marker for intestinal metaplasia) and MUC4 (i.e., marker for spasmolytic polypeptide expressing metaplasia (SPEM)) seen in the adjacent non-tumor tissues suggest the presence of metaplastic changes in these peritumoral sites." (PMID 37085819, 2023). "MUC4 expression and AKT Thr308 phosphorylation were upregulated in the remaining tumor tissues." (PMID 37324940, 2023).